TRAF4 (TNF receptor associated factor 4)
Diseases named in the same sentence as TRAF4 in open-access papers (continued):
Sharing a sentence is not in itself a finding about the gene and the disease.
lung carcinoma (17 papers, 2014 to 2023). "Our findings extended a previous report that miR-370 inhibits the progression of NSCLC by targeting the TRAF4, but disagreed with a previous report that miR-370 expression is associated with poor prognosis of lung cancers." (PMID 29152147, 2017). "To further evaluate the impact of TRAF4 expression on the prognosis of lung cancer patients, we retrospectively studied the survival time of these patients, and found that a higher expression level of TRAF4 was associated with shorter progression‐free survival (PFS)." (PMID 35748027, 2022). "We report that CD44 cleavage in A549 lung cancer cells and other cells is promoted by transforming growth factor-beta (TGFβ) in a manner that is dependent on ubiquitin ligase tumor necrosis factor receptor-associated factor 4 or 6 (TRAF4 or TRAF6, respectively)." (PMID 33804427, 2021). "Overexpression or amplification of TRAF4 has been observed in lung cancer, osteosarcoma, glioma and other tumors." (PMID 36765039, 2023). "Previous study indicated that TRAF4 is an important factor mediating the activation of the AKT pathway in lung cancer." (PMID 36077559, 2022). "In subsequent experiments, both in vivo and ex vivo data demonstrated that TRAF4 strongly promoted the expansion of cancer cells, clearly indicating an oncogenic role of TRAF4 on lung cancer." (PMID 35748027, 2022). "Considering the findings from clinical and experimental data, we conclude that TRAF4 plays a novel and essential role in facilitating lung cancer cell proliferation." (PMID 35748027, 2022). "TRAF4 reduces lung cancer glucose metabolism by inhibiting AKT pathway-mediated expression of Glut1 and HK2." (PMID 35242717, 2022). "It was reported that in lung cancer cells, TRAF4 facilitates cancer development by modifying the tumour microenvironment in normal fibroblasts." (PMID 34983361, 2022). "TRAF4 is overexpressed in lung cancer and is essential for lung cancer cells to maintain tumorigenic properties such as glycolysis and xenograft tumor growth." (PMID 35242717, 2022). "To confirm the critical role of EGFR in TRAF4‐mediated proliferation of lung cancer cells, we deleted the Egfr gene in the TRAF4 inducible A549 cell line." (PMID 35748027, 2022). "To confirm the oncogenic role of TRAF4 in the expansion of lung cancer cells, we initiated Traf4−/− cell from the lung cancer cell line A549 via the Crisper/Cas9 lentivirus system and studied their growth in animal models." (PMID 35748027, 2022). "Previous studies suggest that TRAF4 promotes epidermal growth factor receptor (EGFR) activation in non‐small cell lung cancer (NSCLC)." (PMID 35748027, 2022). "At the RNA level, we observed that ALDOA coordinates with TRAF4 or DUSP4 in a TCGA lung cancer patient cohort." (PMID 32188842, 2020). "TRAF4 promotes lung cancer aggressiveness by modulating the tumor microenvironment in normal fibroblasts via the TRAF4-NOX2/NOX4/p47-phox-ROS pathway." (PMID 30294322, 2018). "Thus, we explored the role of EGFR/TRAF4‐mediated ERK5 activation in the proliferation of lung cancer cells." (PMID 35748027, 2022). "In this study our data strongly suggest that TRAF4 has a putative oncogene function in lung cancer." (PMID 35748027, 2022). "TRAF4 is a crucial molecule for AKT activation in lung cancer." (PMID 35242717, 2022). "Also, YY1-induced ZFPM2-AS1 has been discovered to promote cell growth in lung cancer by upregulating TRAF4." (PMID 34863279, 2021). "Finally, we demonstrated a model in which ALDOA coordinates with DUSP4/TRAF4 and is correlated with a poor prognosis in lung cancer patients." (PMID 32188842, 2020). "More importantly, TRAF4 is confirmed to promote the development of lung cancer." (PMID 32280300, 2020). "Thus, ALDOA regulates the stemness properties of lung cancer cells via the Oct4-DUSP4/TRAF4 axis." (PMID 32188842, 2020). "In lung cancer cells, TRAF4 activates AKT through ubiquitination and is a candidate molecular target for the prevention and therapy of lung cancer." (PMID 34983361, 2022).
lung carcinoma (continued). "ZEB1, TRAF4, and TGF-β1 are involved in lung cancer metastasis by EMT proteins while PD-L1, EGFR, TLR7 and TLR8 are involved in inhibiting the immune system." (PMID 36032679, 2022). "The cleavage of the hyaluronan receptor CD44 is mediated by TRAF4 via the activation of RAC1, promoting migration of A549 lung cancer cells." (PMID 33804427, 2021). "We present here a TRAF4/6-dependent mechanism for how CD44 is cleaved, and demonstrate that the cleavage occurs at increased rate in stem-like A549 lung cancer cells grown in spheres." (PMID 33804427, 2021). "Furthermore, by combining those genes into a significant prognostic factor for lung cancer patients, we determined that ALDOA, together with TRAF4 or DUSP4, serves as an independent factor for the meta-base and TCGA lung cancer patient cohorts." (PMID 32188842, 2020).
glioma (15 papers, 2018 to 2025). A benign or malignant brain and spinal cord tumor that arises from glial cells (astrocytes, oligodendrocytes, ependymal cells). "The abnormal decrease in miR-29a/b/c is an important cause of TRAF4 overexpression and plays crucial roles in the tumorigenesis and malignant progression of gliomas." (PMID 30348972, 2018). "Furthermore, miR-29a controls the platelet-derived growth factor (PDGF) pathway and targets TNF receptor-associated factor 4 (TRAF4)/Akt signaling, which inhibits the stemness and tumor formation of glioma cells." (PMID 39809835, 2025). "Furthermore, the TCGA database also shows that the gene copy number gain for TRAF4 was linked to high expression of TRAF4 in glioma." (PMID 36077559, 2022). "CAV1 also interacts with other proteins to affect glioma cancer progression, it interacts with TRAF4, an E3 ubiquitin ligase, to maintain its deubiquitylation and stability, thus driving glioma stemness and Temozolomide resistance." (PMID 37642765, 2023). "Here, our research suggested that TRAF4 expression was positively correlated with glioma grade and malignant subtype." (PMID 36077559, 2022). "To characterize TRAF4 in gliomas, we analyzed data from the TCGA, CGGA, Rembrandt, and Gravendeel database." (PMID 36077559, 2022). "Through the Wnt signaling pathway, TRAF4 promotes cancer cell invasion in colorectal cancer and glioma." (PMID 35242717, 2022). "To investigate the relationship between TRAF4 expression and prognosis of glioma patients, we analyzed the survival data of glioma patients in the TCGA and CGGA databases." (PMID 36077559, 2022). "Correlation analysis in TCGA and CGGA glioma clinical databases also suggested that TRAF4 was significantly positively correlated with SETDB1." (PMID 36077559, 2022). "In both databases, we found that glioma patients with high TRAF4 expression had significantly shorter survival time than those with low TRAF4 expression." (PMID 36077559, 2022). "Collectively, our analysis of glioma databases and Western blot experiments revealed that TRAF4 is overexpressed in glioblastoma and high expression predicts poor prognosis in patients." (PMID 36077559, 2022). "TRAF4 expression in glioblastoma was significantly higher than that in other low-malignancy gliomas." (PMID 36077559, 2022). "Through AKT or PI3K/AKT signaling pathway, TRAF4 promotes cancer cell migration and invasion in breast, liver, lung, endometrial, osteosarcoma, glioma, and ovarian cancers." (PMID 35242717, 2022). "Here, we found that TRAF4 expression correlates with glioma subtype and grade, and that TRAF4 is significantly overexpressed in glioblastoma and predicts poor prognosis." (PMID 36077559, 2022). "To further validate the experimental conclusions, we explored the relationship between TRAF4 and these growth- and metastasis-related genes in the glioma clinical databases TCGA and CGGA." (PMID 36077559, 2022). "CEBPA and TRAF4 are both over-expressed in glioma cells and tissues, and show a positive correlation with the pathological grade of glioma." (PMID 33109195, 2020). "The PIWIL3/piR-30188/OIP5-AS1/miR-367-3p/CEBPA/TRAF4 pathway can regulate the biological behavior of glioma cells." (PMID 31399034, 2019). "piR-30188 binds the lncRNA OIP5-AS1 and inhibits OIP5-AS1 expression, thereby suppressing glioma cell malignant phenotype via the miR-367/CEBPA/TRAF4 pathway." (PMID 31399034, 2019). "In summary, our study indicates that miR-29a/b/c promote apoptosis and inhibit the proliferation of glioma cells by the direct targeting of TRAF4." (PMID 30348972, 2018). "The prognostic value of TRAF4 in gliomas was further validated by data from TCGA database (OS: P < 0.0001; DFS: P < 0.01)." (PMID 30348972, 2018).
glioma (continued). "A functional study verified that miR-29a/b/c induced apoptosis and suppressed the proliferation of glioma cells by directly targeting TRAF4." (PMID 30348972, 2018). "The silencing effects of the miRNAs were confirmed in U87MG and SNB19 cells by dual-luciferase reporter assays (P < 0.05–0.001), which indicated that TRAF4 was a direct target of miR-29a/b/c in glioma cells." (PMID 30348972, 2018). "This strongly indicates that miR-29a/b/c and TRAF4 are important regulators of glioma cell proliferation." (PMID 30348972, 2018). "The IHC results showed that the TRAF4 level was higher in gliomas than in the controls (P < 0.001) and continued to increase as the glioma grade increased (P < 0.001)." (PMID 30348972, 2018). "This conclusion was further supported by the luciferase assay results which confirmed that TRAF4 was a natural target of miR-29a/b/c in glioma cells." (PMID 30348972, 2018). "Based on these findings, we conclude that miR-29a/b/c suppress G1/S-phase transition and the proliferation of glioma cells by targeting TRAF4 and down-modulating the AKT/GSK-3β pathway." (PMID 30348972, 2018). "In the present study, we demonstrated that miR-29a/b/c effectively induced apoptosis and inhibited the proliferation of glioma cells by targeting TRAF4, and thereby we validated the miR-29 members as important glioma suppressors." (PMID 30348972, 2018). "In this study, we verified that the expression levels of miR-29a/b/c and TRAF4 were closely correlated with tumor grade and proliferation index, which suggests that they can be used as accessory indicators for glioma grading." (PMID 30348972, 2018). "In this study, we confirmed that miR-29a downregulation caused TRAF4 and subsequent Akt activation in gliomas, and miR-29a itself inhibited GBM cell proliferation, migration, and invasion through directly targeting TRAF4." (PMID 30186853, 2018). "To further explore the pathway through which miR-29a/b/c suppress glioma cell proliferation, we focused on the crucial effectors downstream of TRAF4, including AKT, GSK-3β, c-Myc, and the G1/S-phase checkpoint regulator cyclin D1." (PMID 30348972, 2018). "Our results underscore the practical values of these molecules as novel biomarkers for glioma grading and prognostic assessment, and imply that miR-29a/b/c and TRAF4 can be used as therapeutic candidates and as a target for malignant glioma, respectively." (PMID 30348972, 2018). "Our results also implied the potential value of miR-29a/b/c and TRAF4 in the prognosis of glioma patients and as potential therapies for malignant gliomas." (PMID 30348972, 2018). "Compared with the control group, both OA treatment and TRAF4 knockout could inhibit liver metastasis of colon cancer cells and reduce the tumorigenicity of glioma cells." (PMID 39716976, 2025). "Moreover, piR-30188 binds to a lncRNA OIP5-AS1 and inhibits its expression, leading to the suppression of glioma cell malignant phenotype via the miR-367/CEBPA/TRAF4 pathway." (PMID 38993562, 2024). "In glioma, TRAF4 promotes cancer cell proliferation and invasion via the Hippo signaling pathway." (PMID 35242717, 2022). "MiR -29a/b/c induces apoptosis and inhibits glioma cell proliferation directly targeting TRAF4." (PMID 35242717, 2022). "As the results showed, the expression of TRAF4 increased with the grade of glioma." (PMID 36077559, 2022). "The expression of TRAF4 in various histological subtypes of gliomas was further analyzed." (PMID 36077559, 2022). "In addition, TRAF4 acts as functional target of miR-29a/b/c in glioma and its expression level was strongly correlated with the prognosis of patients." (PMID 32065218, 2020).
glioma (continued). "Therefore, PIWIL3/piR-30188 regulates the glioma cell malignant phenotype via the OIP5-AS1/miR-367/CEBPA/TRAF4 pathway." (PMID 31399034, 2019). "Moreover, the inverse correlations between the levels of miR-29a/b/c and TRAF4 imply that the abnormal decrease in miR-29s is responsible for the overexpression of TRAF4 in gliomas." (PMID 30348972, 2018). "There is only one fusion of TRAF4 detected in human cancers, the TRAF4-FASN fusion identified in a glioma patient (TCGA), with currently unknown functional significance." (PMID 30294322, 2018). "To determine whether TRAF4 silencing mediates the adverse effects of miR-29a/b/c on glioma cell proliferation, we transfected the mixture of the miR-29a/b/c-overexpressing sub-cell lines (miR-29s) with the TRAF4-expressing plasmid (miR-29s + TRAF4)." (PMID 30348972, 2018). "To better understand the interplay of TRAF4 and miR-29a in gliomas, we investigated whether TRAF4 or Akt activation might exert some effects on the tumor suppressor miR-29a." (PMID 30186853, 2018). "Mechanistically, we verified TRAF4 as a direct target of miR-29a in gliomas, which could further mediate Akt pathway activation." (PMID 30186853, 2018). "However, to the best of our knowledge, the expression pattern of TRAF4 in gliomas and its exact roles in gliomagenesis remain largely elusive." (PMID 30348972, 2018). "Moreover, in our glioma specimens, the TRAF4 level was negatively correlated with the miR-29a/b/c levels (miR-29a: r = −0.858; miR-29b: r = −0.864; miR-29c: r = −0.870; P < 0.0001)." (PMID 30348972, 2018). "miR-29s and TRAF4 are potential biomarkers for glioma grading and prognosis." (PMID 30348972, 2018). "In our pathologic analysis, we also found that the Ki-67 index, a widely accepted scale for proliferation, was not only increased as the glioma grade increased but also inversely correlated with miR-29a/b/c levels and was positively correlated with the TRAF4 level." (PMID 30348972, 2018). "Low OIP5-AS1 expression increases miR-367-3p expression, thereby decreasing CEBPA, which facilitates glioma development by binding to the promoter of TRAF4 (which promotes cancer proliferation, migration, and invasion and inhibits apoptosis), ultimately weakening TRAF4 expression." (PMID 31399034, 2019). "Furthermore, TRAF4-knockdown perfectly simulated the anti-glioma effects of miR-29a/b/c." (PMID 30348972, 2018). "Additionally, transient knockdown of endogenous TRAF4 with specific siRNAs (P < 0.001) perfectly simulated the suppressive effects of miR-29a/b/c on cell cycle progression and glioma cell proliferation, which were also partially reversed by TRAF4 overexpression (P < 0.01–0.001)." (PMID 30348972, 2018). "Kaplan–Meier analyses demonstrated that a higher TRAF4 level predicted a shorter DFS (P < 0.0001) and OS (P < 0.0001) of our glioma patients." (PMID 30348972, 2018). "MiR-29a is critical tumor suppressor for glioma tumorigenesis by forming a negative feedback loop of TRAF4/Akt signaling and represents a potent therapeutic candidate for treating gliomas." (PMID 30186853, 2018). "TRAF4 has recently been found to promote tumorigenesis through the activation of the central signaling node AKT32,33, which is one of the most pivotal and versatile protein serine/threonine kinases at the core of glioma pathogenesis." (PMID 30348972, 2018). "Western blot results showed that TRAF4 was higher in glioma samples compared to noncancerous tissues, keeping on increasing with the elevation of tumor grade." (PMID 30186853, 2018). "We showed a significantly negative expression correlation between TRAF4 and miR-29a in normal and glioma tissues." (PMID 30186853, 2018). "Moreover, we found that miR-29s-induced TRAF4 knockdown markedly blocked the phosphorylation of AKT and GSK-3β as well as the expression of cyclin D1 and c-Myc in glioma cells." (PMID 30348972, 2018).
glioma (continued). "Our study contributes to clarify the tumor suppressing function of miR-29 through forming a negative feedback loop of TRAF4/Akt signaling, and miR-29a represents a potent therapeutic target for treating gliomas." (PMID 30186853, 2018). "We also observed a negative feedback loop between miR-29a and TRAF4/Akt signaling, suggesting miR-29a as a potent therapeutic candidate for gliomas." (PMID 30186853, 2018). "This forms a negative feedback to control TRAF4/Akt levels in glioma." (PMID 30186853, 2018). "MiR-29a is a crucial tumor suppressor in gliomagenesis by forming a negative feedback loop for TRAF4/AKT signaling, inhibits cell proliferation, migration, and invasion, and is an effective candidate for the treatment of glioma." (PMID 35242717, 2022).
hepatocellular carcinoma (11 papers, 2017 to 2026). A malignant tumor that arises from hepatocytes. "In addition, TRAF4 activated the PI3K/AKT signaling pathway to promote the migration and invasion of hepatocellular carcinoma cells, and clinical evidence suggested that TRAF4 was closely associated with poor prognosis in intrahepatic cholangiocarcinoma." (PMID 36765039, 2023). "Overexpression of TRAF4 can modify the phosphorylation of Akt as well as the expression of Slug, E-cadherin, and vimentin in hepatocellular carcinoma cells." (PMID 36625999, 2023). "The oncogene TRAF4 has been widely studied in a variety of cancers, such as hepatocellular carcinoma cholangiocarcinoma, and non-small cell lung cancer." (PMID 33817231, 2020). "TRAF4, TNF receptor associated factor 4, is targeted by miR-302c-3p and overexpressed in hepatocellular carcinoma." (PMID 32065218, 2020). "In hepatocellular carcinoma, TRAF4 regulates migration, invasion, and the EMT process via PI3K/Akt/mTOR signaling pathway." (PMID 28864782, 2017). "MiR-302c-3p exerts tumor-suppressive effects in hepatocellular carcinoma by targeting TRAF4." (PMID 35242717, 2022). "TRAF4 is more highly expressed in hepatocellular carcinoma (HCC) cell lines and tissues than regular hepatocyte lines and adjacent non-cancerous tissues." (PMID 35242717, 2022). "Inhibition of the miR-302c-3p/TRAF4 axis may be a therapeutic target for hepatocellular carcinoma." (PMID 35242717, 2022). "TRAF4 was reported to promote cell migration and invasion by activating the PI3K/Akt signaling pathway in hepatocellular carcinoma." (PMID 36625999, 2023). "Previous studies identified miR-21-3p target genes: in ovarian cells it targets NAV3, a known tumor suppressor; in hepatocellular carcinoma, it targets SMAD7, an inhibitor of the TGFβ pathway; and in ESCC, it targets TRAF4." (PMID 34797887, 2021). "TRAF4 has been found to promote TGFβ signaling via Smad and non-Smad pathways, and to promote the migration of hepatocellular carcinoma, as well as endothelial and epithelial cells." (PMID 33804427, 2021).